STAT3 (signal transducer and activator of transcription 3)
Diseases named in the same sentence as STAT3 in open-access papers (continued):
Sharing a sentence is not in itself a finding about the gene and the disease.
colon carcinoma (continued). "GO-Y030 and curcumin inhibited STAT3 phosphorylation, cell viability, tumoursphere formation in colon cancer stem cells." (PMID 21694723, 2011). "Other cancer related genes include the TFF3 gene, which was shown to activate STAT3, (an oncogene) signaling in human colonic cancers and the VEGF receptor FLT1 gene." (PMID 19458770, 2007). "Here, we examined the ability of TTI-101 to treat CRC in the AOM-DSS mouse model of colitis-induced CRC and demonstrated that TTI-101 markedly reduced colon tumors in this model, at least in part, by normalizing the STAT3-driven pro-oncogenic transcriptome in colonic mucosa." (PMID 41226842, 2025). "Likewise, SESN2 is found downregulated in colon cancer, where STAT3 is often hyperactivated and contributes to carcinogenesis." (PMID 39985075, 2025). "In addition, ICAM1 neutralizing antibodies have also been found to inhibit SRC and STAT3 pathways and inhibit colon tumor metastasis and angiogenesis." (PMID 39971940, 2025). "Besides the well-known pro-inflammatory IL-6 cytokine, TNF-α was found to promote proliferation and inhibit apoptosis in colon cancer cells by activating STAT3." (PMID 39641861, 2025). "Research has demonstrated that oxidative stress induced by nitrogen and oxygen compounds within the inflammatory microenvironment, coupled with the activation of NF-κB and STAT3 signaling pathways by inflammatory mediators, plays a crucial role in the progression from colitis to colon cancer." (PMID 40487290, 2025). "For example, A. finegoldii administration demonstrated marked efficacy in symptom amelioration within the DSS-induced colitis murine model, but it may also promote right-sided colon cancer through the IL-6/STAT3 pathway." (PMID 40509521, 2025). "Previous investigations from our research team demonstrated that the combination of FLCWK with 5‐FU suppressed the proliferation and induced apoptosis in colon cancer cells by modulating the IL‐6/STAT3 signalling pathway, resulting in the inhibition of colon tumour growth in CAC mice." (PMID 39495702, 2024). "In colon cancer, CLDN6 activates the TYK2/STAT3 pathway, which might suppress the migration and invasion abilities of colon cancer cells." (PMID 38731853, 2024). "Furthermore, SFN displayed significant antioxidant and chemopreventive activities by inhibiting the IL-1β-induced expression of IL-6 and the subsequent MAPK/AP-1/STAT3 signaling in HT-29 colon cancer cells." (PMID 38671854, 2024). "Additionally, GENET has successfully predicted WNT family member 4 regulates insulin‐like growth factor 2 via signal transducer and activator of transcription 3 in colon cancer." (PMID 39373342, 2024). "In human colon cancer cells, ectopic STAT3 expression increased ID1 mRNA and protein expression." (PMID 38183094, 2024). "It is assumed that the miR-34c-5p/SIRT6/JAK2/STAT3 axis could be an innovative therapeutic target that opens new insights into developing treatment approaches for colon cancer therapy." (PMID 38185635, 2024). "Moreover, α-Hederin was shown to inhibit the proliferation, invasion, and migration of colon cancer cells SW620 by regulating the JAK2/STAT3 signaling pathway." (PMID 38244586, 2024). "This study suggested that miR-181b/PIAS3/STAT3 axis may be a key target for colon cancer therapy regarding its effect on cell growth and metabolism." (PMID 38185635, 2024). "Moreover, in colon cancer cells, STAT3 was reported to function as an upstream regulator of lncRNA HOTAIR and increase the expression of this oncogenic lncRNA." (PMID 38185635, 2024). "Further analyses showed that STAT3 shRNA reduced the viability of colon cancer-initiating cells." (PMID 38067351, 2023). "As the IL-6/STAT3 pathway is an important pathway that regulates the progression of colon cancer, inhibition of this pathway by Luteolin provided new insight into the therapeutic potential and mechanisms of Luteolin for colon cancer treatment." (PMID 36992138, 2023).
colon carcinoma (continued). "Furthermore, macrophage-induced IL-6 favored the migration and invasion of colon cancer cell via WNT/β-catenin in a STAT3/ERK-dependent manner." (PMID 36980226, 2023). "Case-control studies, using more than 1550 patients with colon cancer and 750 cases of rectal cancer, demonstrated that JAK2, SOCS2, STAT1, STAT3, STAT5A, STAT5B, and STAT6 were associated with colon cancer, and that STAT3, STAT4, STAT6, and TYK2 were linked to rectal cancer." (PMID 36982677, 2023). "To determine whether the ZEB1 and integrin α3 is regulated by STAT3 signaling in colon cancer cells, we used two independent siRNAs to knock down STAT3’s expression and then examined the expression of ZEB1, integrin α3 and GOLPH3 in HCT116 and HCT8 cells." (PMID 35372504, 2022). "In order to study the effects of LINC00858 on the tumorigenicity of colon cancer cells by regulating the RAD21/PCNP/STAT3/5 axis in vivo, we injected SW480 cells transduced with adenovirus carrying oe-NC + sh-NC, oe-LINC00858 + sh-NC, oe-LINC00858 + sh-RAD21, oe-LINC00858 + sh-PCNP into nude mice." (PMID 35468892, 2022). "In addition, radiation treatment can promote the radiation resistance of colon cancer stem cells through the activation of JAK2/STAT3/CCND2 signaling pathway." (PMID 36199626, 2022). "Therefore, cirsiliol is a potential candidate for the treatment of colon cancer and works by inhibiting mitophagy via STAT3 signaling." (PMID 36207761, 2022). "Essential inflammatory pathways such as STAT3 are understood to be drivers of inflammation and tumorigenesis, and diving into the crosstalk of these pathways advances our understanding of the complex links between inflammation and colon cancer." (PMID 36146640, 2022). "Besides, our results showing nuclear translocation of CypB and following co-localization with lncPVT1 in response to IL-6 treatment indicate potential roles of lncPVT1 and CypB in mediating activation of STAT3 in colon cancer cells." (PMID 36266267, 2022). "Cirsiliol targets STAT3 to inhibit colon cancer cell proliferation by regulating mitophagy." (PMID 36207761, 2022). "Moreover, the IL6/JAK/STAT3 pathway has been found to upregulate CXCL1, CXCL2, CXCL3, and CXCL11 in patients with colon cancer, which was associated with prognosis." (PMID 35468892, 2022). "In addition, the results of cell cloning and cell migration were also consistent, indicating that further overexpression of STAT3 would offset the inhibitory effect of 50 μmol/L diosgenin on colon cancer cells." (PMID 35698571, 2022). "In addition, a previous study demonstrated that HPGD suppresses colon cancer aggressiveness through the STAT3 and AKT pathways." (PMID 35317779, 2022). "IL-6 has been shown to contribute to STAT3 activation in colon cancer." (PMID 36207761, 2022). "Growth of colon cancer cells is suppressed when DNA binding of activated STAT3 is prevented." (PMID 35626167, 2022). "Moreover, after diosgenin treatment on colon cancer cells, the STAT3 expression was markedly reduced." (PMID 35698571, 2022). "Participate in the Stat3 signaling pathway and promote colon cancer progression." (PMID 35992805, 2022). "In addition, RIG-1 activation inhibited STAT3/CSE pathway activity to restrain the proliferation of colon cancer cells." (PMID 36601407, 2022). "Downregulation of FER inactivated STAT3 in colon carcinoma cells." (PMID 34295819, 2021). "Taken together, overexpression of ZNF460 predicted worse survival and promoted metastasis through JAK2/STAT3 signaling pathway in patient with colon cancer, and could be a novel therapeutic target in colon cancer." (PMID 33976729, 2021). "Importantly, Meg3 acts as a ceRNA for miR-708, leading to enhanced expression of SOCS3, which in turn suppresses STAT3 signaling and malignant proliferation of colonic stem cells during the early stage of colon tumor formation." (PMID 34934045, 2021).
colon carcinoma (continued). "Furthermore, immunohistochemistry (IHC) analyses showed that CREPT and p-STAT3 were both strongly stained in the nucleus in breast and colon cancer tissues." (PMID 33531691, 2021). "STAT3 and P65 are activated in colonic tumor tissues from patients." (PMID 33882644, 2021). "By this, activated STAT3 may participate in tumor progression through increasing CD133/Survivin expression in early stage of colon cancer development." (PMID 33557398, 2021). "Since STAT3 is a potential drug target for colon cancer therapy, therefore, the purpose of our study was to explore the combination effect of AF and ICG-001 on colon cancer and the underling mechanism related to STAT3." (PMID 34900688, 2021). "HIF and p-STAT3 are upregulated in mice and human colon cancer cells, and HIF could promote colon cancer cell proliferation by activating JAK-STAT3 pathway." (PMID 33029691, 2021). "In addition, activated signal transducer and activator of transcription 3 (STAT3) participates in early stage of colon cancer progression by upregulation of the stem cell marker CD133 that in turn induces Survivin expression." (PMID 33557398, 2021). "ZNF460 overexpression was significantly associated with poor prognosis and increased metastatic capabilities of human colon cancer by activating JAK2/STAT3 signaling pathway, and ZNF460 might act as a potential prognostic biomarker and therapeutic target." (PMID 33976729, 2021). "Our results indicated that ORI disrupted the JAK2/STAT3 signaling pathway in colon cancer." (PMID 33976735, 2021). "Further, a study on patients with inborn mutations in their STAT1 genes, and of the potential cross-regulation mechanisms between STAT1 and STAT3, may provide novel therapeutic strategies against colon cancer." (PMID 34299314, 2021). "Our results show that LPE is able to inhibit the IL-6-dependent cell migration and invasiveness associated with the up-regulation of MMP-2 expression levels and that these effects are correlated to the STAT3 phosphorylation in human primary T88 and T93 colon cancer cells." (PMID 34885656, 2021). "PTPRD acts as a regulator for STAT3, which is shown to be activated in colon tumors and cell lines." (PMID 34503185, 2021). "Therefore, SND can directly(binding) or indirectly (with microbiota) downregulate the NF-κ-B/STAT3, and decrease the DNA damage, subsequently restraining the formation and expansion of colon tumors." (PMID 33776762, 2021). "The low level of p-STAT3 could downregulate the expression of Bcl-xL, and then induce Caspased-3-dependent apoptosis of colon cancer cells." (PMID 34900688, 2021). "Similarly, overexpression of ZNF460 predicts worse survival and promotes metastasis through JAK2/STAT3 signaling pathway in patients with colon cancer." (PMID 34638319, 2021). "Moreover, STAT3 and its target gene products, including Bcl-xl, have been found to be overexpressed in colon cancer cells." (PMID 34443375, 2021). "In colon cancer, knockdown of STAT3 reversed BMP2-induced CSC formation." (PMID 34277708, 2021). "These indicated that the synergistical antitumor effect of the AF and ICG-001 combination could be exerted by inducing caspase-3-dependent apoptosis via directly inhibiting phosphorylation of STAT3 of colon cancer cells." (PMID 34900688, 2021). "In addition, propofol attenuates metastasis of colon cancer by STAT3/HOTAIR axis through the activation of WIF-1 and the suppression of Wnt signaling." (PMID 34789263, 2021). "Majority of the target genes with enhanced binding of STAT3del showed significantly higher expression, whereas majority those that showed reduced STAT3del binding demonstrated significantly reduced expression in the three colon cancer cells with STAT3del compared to those with wild-type STAT3." (PMID 33535185, 2021).
colon carcinoma (continued). "In conclusion, our study demonstrated that the combination therapy of AF and ICG-001 could significantly suppress the proliferation and metastasis of colon cancer in vitro and in vivo via directly inhibiting phosphorylation of STAT3." (PMID 34900688, 2021). "Flavonoid morin and telomerase inhibitor (MST-312) are two potential therapeutic compounds which have been found to lower tumourigenicity of CSCs by targeting signal transducer and activator of transcription 3 (STAT3) and telomerase in human colon cancer cells." (PMID 32503256, 2020). "Taken together, these results suggest that FXR activation might suppress JAK2/STAT3 pathway in colon cancer cells by up‐regulating SOCS3 expression." (PMID 33164339, 2020). "Similarly, in response to IL6, dimethylation of STAT3 at lysine 49 by EZH2 also promotes transcription of STAT3 targets in colon cancer." (PMID 33327550, 2020). "Importantly, BC200 downregulation inhibits EMT in HCT-116 and HT29 colon cancer cells in part via the suppression of STAT3 phosphorylation." (PMID 33246471, 2020). "We revealed that propofol could suppress the development and metastasis of colon cancer by blocking the interaction of STAT3 with HOTAIR promoter and downregulating the expression of HOTAIR, which causes the repression of Wnt signaling pathway via WIF‐1." (PMID 31953926, 2020). "The results strongly indicated that FLCWK could increase the phosphorylation of STAT3 with 5-FU, inhibit signal transduction of IL-6/STAT3, and further induce apoptosis and antiproliferative effects in colon cancer cells." (PMID 33082817, 2020). "We thus concluded that FLCWK could synergize with 5-FU and inhibit suppressed IL-6/STAT3 signalling by attenuating the phosphorylation of STAT3 and further exerting apoptosis-inducing and antiproliferative effects on colon cancer cells." (PMID 33082817, 2020). "LY5 inhibited STAT3 phosphorylation and suppressed colon tumor growth in vivo." (PMID 32872659, 2020). "Since low surface expression of CD80 is an immunoescape mechanism of colon carcinoma, we speculate that the tumor suppressor role of STAT3 in the later stages of colon cancer progression may be explained by its ability to enhance CD80 expression." (PMID 31072360, 2019). "We next studied whether tRXRα activation of the IKK-NF-κB inflammatory pathway in macrophages could serve to activate STAT3 in colon cancer cells." (PMID 30931933, 2019). "Activation of STAT3 has been shown to promote proliferation of colon cancer cell lines." (PMID 31402975, 2019). "Furthermore, the phosphorylation levels of STAT3 and NF‐κB p65 were enhanced in GM‐Exo‐treated colon cancer cells, but the levels of p‐STAT3 and p‐p65 were decreased in GM‐Exo subjected to S100A9 knockdown." (PMID 31559140, 2019). "Furthermore, we identified numerous CTS transcriptional signatures whose expression was significantly associated with prognosis in colon cancer, such as CEBPB, PPARGC1, STAT3, MTOR, BCL2, JAK2, and CDK1." (PMID 31186640, 2019). "The in vivo study showed that HBD could significantly reduce the mortality of mice and control the incidence and size of colonic tumors by inhibiting the IL-6/STAT3 signaling pathway." (PMID 30832202, 2019). "Our data suggests that colon cancer cells are able to promote self-growth through the secretion of exosomes, especially under hypoxic conditions, which shortens mitosis duration and activates STAT3." (PMID 31402975, 2019). "In the present study, we investigated posttranslational regulatory mechanisms downstream of the IL-6/STAT3/FRA1 inflammatory signaling axis that mediate colon cancer stemness and malignancy and explored novel combinatorial therapeutic approaches to target CRC stem and bulk cells." (PMID 30804456, 2019).
colon carcinoma (continued). "In addition, biofilm has been associated with decreased expression of E-cadherin on colonic epithelial cell, an over activation of IL-6 and Stat3 in epithelial cell, all these mechanisms are involved in colon cancer." (PMID 31662752, 2019). "Another study indicated that ectopic expression of miR-1299 could downregulate STAT3 pathway to inhibit colon cancer cell growth." (PMID 30946694, 2019). "Inhibition of STAT3 significantly inhibited the sphere formation of CSCs in colon cancer." (PMID 30962766, 2019). "Finally, Exo-hypoxic treatment induced stronger STAT3 activation and shorter mitosis duration in colon cancer cells than Exo-normoxic." (PMID 31402975, 2019). "In addition, ALO inhibits phosphatidylinositol 3-kinase/Akt and JAK/Stat3 pathways, inducing apoptosis in colon cancer cells." (PMID 31534865, 2019). "We also found that IL-32θ inhibited the STAT3 pathway-mediated colon cancer stemness." (PMID 31263095, 2019). "Collectively, we develop a multifunctional nanoparticle formulation of afatinib and miR-139 with targeting, penetrating, and pH-responsive characteristics for simultaneous modulation of EGFR/HER/Ras/Akt/Rac1/STAT3/MAPK/EMT/Bcl-2 pathways to increase the sensitivity of colon cancer cells to afatinib." (PMID 31426807, 2019). "The previous study demonstrated that aloperine induced a G2/M-phase cell cycle arrest, and inhibited Janus kinase (JAK)/Signal transducer and activator of transcription 3 (Stat3), phosphatidylinositol 3-kinase/Akt, as well as Bcl-2, in a human colon cancer cell line." (PMID 29361731, 2018). "Additionally, PKM2 reduces the sensitivity of colon cancer cells to gefitinib via the phosphorylation of STAT3." (PMID 30257458, 2018). "Moreover, a positive feedback loop between miR‐181b and STAT3 that regulated the Warburg effect in colon cancer was explored." (PMID 30054984, 2018). "Moreover, a positive feedback loop between miR‐181b and STAT3 that regulated the Warburg effect in colon cancer was also demonstrated." (PMID 30054984, 2018). "Moreover, a miR‐181b‐STAT3 positive feedback loop that contributed to the Warburg effect in colon cancer cells was demonstrated as well." (PMID 30054984, 2018). "The aim of this study was to determine whether Teucrium essential oil led to antitumor activity by abrogating the STAT3 signaling pathway in colon cancer cells." (PMID 30190788, 2018). "This study suggested miR‐181b/PIAS3/STAT3 axis as a novel target for colon cancer treatment." (PMID 30054984, 2018). "Moreover, a positive feedback loop between miR‐181b and STAT3 regulating the Warburg effect in colon cancer was demonstrated." (PMID 30054984, 2018). "This hypothesis not only clarified the mechanism underlying the role of miR‐181b in the activation of STAT3, but also provided a theoretical basis for the persistent activation of STAT3 in colon cancer." (PMID 30054984, 2018). "The gain‐of‐function and loss‐of‐function experiments were performed on HCT 116 cells to investigate the effect of miR‐181b/PIAS3/STAT3 on the Warburg effect and xenograft tumour growth of colon cancer, as determined by commercial kits and xenograft experiments." (PMID 30054984, 2018). "DB-medicated CSC-inhibitory effects were associated with the decreased expression of the IGF downstream oncogenic marker, mTOR/STAT3, as well as the stemness marker, β-catenin, both of which have been reported to contribute to treatment failure and the recurrence of colon cancer." (PMID 30257507, 2018). "For instance, genetic and pharmacological studies confirmed that the expression of CLDN3 was downregulated in colon cancer and that the loss of CLDN3 induced Wnt/β-catenin activation in a transducer and activator of transcription 3 (Stat3)-dependent manner to promote colon cancer malignancy." (PMID 30219077, 2018). "Exploring the phosphorylation of CREB and STAT3 in relation to MUC2 might reveal associations between MUC2 and IL-6 in colon cancer." (PMID 28725043, 2017).